CASP9 (caspase 9)
Diseases named in the same sentence as CASP9 in open-access papers (continued):
Sharing a sentence is not in itself a finding about the gene and the disease.
cancer (continued). "ScRNA-Seq analysis supported these findings: indeed, cancer cell clusters of shTFEB tumors had lower expression of the pro-apoptotic genes Bax, cytochrome c and caspase 9, known to be upregulated by PT." (PMID 39107857, 2024). "Cancer cells typically evade cell death by upregulating antiapoptotic proteins like BCL-2 or inhibiting pro-apoptotic proteins such as Casp9." (PMID 39005932, 2024). "Both Caspase-3 activity and Caspase-9 activity were significantly increased in MB-10 (25 μM)-treated priBlCa-1 primary cancer cells." (PMID 38467612, 2024). "Downregulation of ERK1/2 and upregulation of the JNK pathways due to CP/PAL are usually accompanied with decreased PI3K/Akt/mTOR pathway and downstream NFκB activity in cancer cells to inhibit proliferation and promote caspase 9/3-dependent apoptosis." (PMID 38785562, 2024). "In cancer models, orexins have been shown to promote apoptosis via the stimulation of caspases, particularly caspase-3 and caspase-9, in several cell lines." (PMID 38699177, 2024). "Compounds 1, 6, 15, and 37 reduced the viability of cell lines via the intrinsic (caspase-9) and extrinsic (caspase-8) pathways of apoptosis, where 16 and 17 mainly influenced DNA biosynthesis in cancer cells." (PMID 38339241, 2024). "As the ECM plays a crucial role in cellular interaction and response to apoptosis-inducing stimuli, several studies on cancer lines have reported an increase in apoptotic markers (Caspase 3, Caspase 7, and Caspase 9) in 3D cells compared to 2D cells." (PMID 39330559, 2024). "Cytotoxicity was tested against liver (HepG2), breast (MCF-7), and intestinal (CACO2) carcinoma cell lines followed by assessment of its impact on the levels of apoptotic markers namely topoisomerase I and caspase 9 enzymes." (PMID 39609685, 2024). "For instance, regulation of pro-apoptotic genes BAX, caspase-3 and caspase-9 is a major event in cancer development and progression." (PMID 37958747, 2023). "Caspase-9 is an initiator caspase and acts on the intrinsic or mitochondrial pathway, which is involved in chemotherapies, functional changes, or cancer development." (PMID 36903346, 2023). "It inhibits the rapid growth, invasiveness, and metastasis of tumors by hindering the multiplication of cancer cells, and prompts apoptosis by avoiding cell division related to actuation of caspase-9 and caspase-8." (PMID 37259344, 2023). "It prompts apoptosis by avoiding cancer cell division related to the actuation of caspase-9 and caspase-8 and permeabilization of the mitochondrial membrane, followed by the splitting of poly (ADP-ribose) polymerase-1." (PMID 37259344, 2023). "Lactobacillus plantarum DGK-17-fermented soybean seed extract can induce cancer cell apoptosis by regulating the protein expression of caspase 9, 3, BCl-2 and Bax, thereby inhibiting HCT-116 cell growth." (PMID 37570647, 2023). "Meanwhile, some of the compounds obtained in our laboratory, such as 3-aryl-2-(1H-benzimidazol-2-yl)acrylonitriles, have been identified as potential caspase-9 activators, possessing cytotoxic activity against human cancer cell lines." (PMID 37513830, 2023). "Nar triggers an increase in the levels of caspase 3, caspase 8, Caspase 9, and BAX expression, all of which are associated with inducing apoptosis in cancer cells." (PMID 38004545, 2023). "Both cleaved-caspase 8 and cleaved-caspase 9 activate caspase 3 to form cleaved-caspase 3, which in turn degrades the DNA repair-associated protein PARP and induces apoptosis in cancer cells." (PMID 36674931, 2023). "Unlike the case with the ER and PR, which must be inhibited, for caspase-9, we tried to study the activation potential of caspase-9 from compound to assess the ability to induce apoptosis of cancer cells." (PMID 37630212, 2023).
cancer (continued). "Treatment-related mortalities are always a concern, even in patients with a limited cancer-related prognosis, but it is hoped that use of strategies such as the caspase-9 suicide switch within the CAR transgene will minimise this in the future." (PMID 37371056, 2023). "The constructs showed anti-cancer activity such as impaired cancer cell viability, reduced migration and induction of apoptosis, and increased caspase 3/7, cleaved caspase 3, and caspase 9 expressions." (PMID 37359373, 2023). "Caspase-9 is a key player in the regulation of intrinsic apoptosis, its activation failure leading to severe diseases including cancer and reflecting the potential development of drug resistance to chemotherapy." (PMID 37958717, 2023). "Via intrinsic and extrinsic (Cyt c/caspase 9) apoptotic mechanisms, emodin reduces the survival of cancer cells." (PMID 37720346, 2023). "Detailed mechanistic studies were performed that reveal that the anti-cancer effects were associated with the downregulation of the expression of VEGF, CYCLIN-D1, and STAT-3 genes and upregulation of the apoptotic Caspase-9 gene." (PMID 35216264, 2022). "Caspase-9 had an important effect on the apoptosis of a variety of cancer cell types, and its positive and negative regulators were reported in the previous literature." (PMID 35211500, 2022). "Clinical reports suggest that alterations in Caspase 9 expression or activation can be involved in several diseases, including cancer." (PMID 36297489, 2022). "It is interesting to note that both API and miR-155 have common apoptotic targets in cancer cells such as caspase 3, caspase 9, FAS and Bcl2." (PMID 35892872, 2022). "UVC/SK2 stimulated more caspase 8 (+) counts, which were higher than caspase 9 (+) in cancer cells (Ca9-22 and OC-2)." (PMID 35625933, 2022). "Several studies have demonstrated that death signaling is regulated by changes in isoform expression due to alternative splicing, particularly in Fas/CD95 and Bcl-x in T cells and caspase-9 in cancer." (PMID 36264057, 2022). "This indicates that DEN injection blocks the apoptosis program through downregulation of caspase-9, but cancer-bearing mice administered with CP-25 and 5-Fu show significantly increased caspase-9 expression." (PMID 35154466, 2022). "Studies have revealed that geraniin exerts significant inhibitory effects on tumor growth and markedly promotes cancer cell apoptosis by increasing the expression of Bax, caspase-3, and caspase-9 and decreasing the level of Bcl-2." (PMID 35222793, 2022). "In many in vitro studies, B. bifidum and L. rhamnosus extracts have been shown to induce apoptosis in human cancer cells through mitochondrial cytochrome c release and cleavage of caspase-9 and -3." (PMID 36077182, 2022). "The serine/threonine phosphatase PP2A and the cysteine protease Caspase 9 are two proteins involved in physiological and pathological processes, including cancer and apoptosis." (PMID 36297489, 2022). "Characterization of genes involved in the caspase 9-independent cell death pathways will likely provide more specific and effective targets for cancer therapy." (PMID 36231015, 2022). "In the present study, cancer-bearing mice showed reduced expression of caspase-9 as compared to normal control mice." (PMID 35154466, 2022). "After affecting the PI3K/Akt pathways, ILTPs also influence Bcl-2, NF-κB, and caspase-9 expression, thereby promoting cancer cell apoptosis." (PMID 35321703, 2022).
cancer (continued). "This is similar to previous studies on other cancers Caspase-9 is a well-known initiator Caspase which triggers intrinsic apoptosis." (PMID 35945549, 2022). "The ROS levels sharply declined in cancer cells provoked the mRNA and protein level of cleaved caspase-9 and Bax." (PMID 36009221, 2022). "Cancer research shows that sulforaphane treatment increases caspase-9 and poly-ADP ribose polymerase (PARP-1) activity, as well as cyclooxygenase IV (COX IV) activity, sensitizing cancer cells to mitochondria-mediated apoptosis." (PMID 36295538, 2022). "Protein kinase CAMP-activated catalytic subunit alpha (PRKACA), elastase neutrophil expressed (ELANE), NLRP1, pejvakin (PJVK), and CASP9 were significantly downregulated in 25, 24, 22, 25, and 23 types of cancers, respectively." (PMID 35246158, 2022). "MIR503HG knockdown remarkably upregulated Bax, Bad, cleaved caspase-3 and cleaved caspase-9 but downregulated Bcl-2 and survivin to promote apoptosis in cancer cells, thus suppressing NSCLC development." (PMID 35379783, 2022). "EME was shown to induce caspase-3, caspase-9/6, and caspase-8, followed by apoptosis induction in different human cancer cell lines." (PMID 36139404, 2022). "CASP9 (caspase-9), a member of the cysteine-aspartic acid protease (caspase) family, was confirmed to play a crucial role in cancer progression." (PMID 35308143, 2022). "At that point, the p38/JNK signalling ‘hub’ can directly activate the mitochondrial caspase-9-dependent pathway, as also reported in other types of carcinoma cells." (PMID 36291141, 2022). "Pharmacological inhibition of caspase-9 can help sensitize cancer cells to chemotherapy by promoting caspase-8-dependent apoptosis." (PMID 34305609, 2021). "Numerous studies indicated that BA has the ability to induce apoptosis in several cancer cells, noted by the upregulation of caspase-9 and caspase-3 activities." (PMID 34770786, 2021). "Further analyses showed that LACBio1, LACBio2, LACBio3 and LACBio4 exert cytotoxic effects on MDA-MB 231 cancer cell line by inducing the intrinsic apoptosis pathway, activating caspase 9 and Bax/Bcl-2 pathway in vitro." (PMID 34361566, 2021). "CASP9, an initiator of intrinsic apoptosis, regulates physiological and pathological cell death in several diseases, including various cancers, neurological disorders, and autoimmune pathologies." (PMID 34910689, 2021). "The birinapant inhibits cIAP1/2 to reactivate caspase-8, and the DEBIO1143 suppresses XIAP to reactivate caspase-9 both facilitates cancer cell apoptosis, which results in synergistic anti-tumor effects in combination with cisplatin (or carboplatin)." (PMID 34026617, 2021). "Caspase-9 is currently a more in-depth study of the caspase promoter, which is closely related to proliferative diseases, degenerative diseases and cancer." (PMID 34876094, 2021). "Caspase-9b expression is upregulated in several cancers, potentially providing an apoptosis-evasion strategy for tumors with high levels of caspase-9 expression." (PMID 34305609, 2021). "CUX1 suppressed the caspase-9 and -3 axis, well-known key effectors of the apoptosis-machinery in cancer in all examined cell lines." (PMID 32707646, 2020). "In conclusion, andrographolide can be considered an anti-cancer compound that targets BCSCs due to its molecular interactions with survivin, caspase-9, and caspase-3, which induce apoptosis." (PMID 33211707, 2020).
cancer (continued). "Expression of Bax and caspase-9 genes revealed a highly significant increase in cancer cell lines (p = 0.0001) when compared to the control group." (PMID 32372389, 2020). "Previous studies showed that Cos induced cancer cell death via stimulation of caspase-8 or caspase-9, depending on cancer cell types or other factors." (PMID 33194716, 2020). "It was reported that survivin and XIAP can form a heterocomplex to stabilize both of them and synergistically antagonize the activity of Caspase 9 to inhibit apoptosis in cancer cells." (PMID 32381104, 2020). "We examined the anti-cancer potential of andrographolide, a natural active compound, through its in silico molecular interactions with survivin, caspase-9, and caspase-3 and the increased intrinsic apoptosis activity of human BCSCs in vitro." (PMID 33211707, 2020). "With anti-cancer effect of Cig, CB13 also causes inhibition of cell growth by decreasing cell viability, increasing the release of LDH, and increasing caspase-3, and caspase-9 activities." (PMID 33051435, 2020). "We find that the regulation of CASP9 through NF-κB-mediated FFL plays a pro-apoptotic role in the TNFα-promoted apoptosis of cancer cells induced by DOX." (PMID 32225068, 2020). "In order to evaluate the mRNA expression levels of apoptotic-associated genes including p-53, caspase-3, caspase-9, Bax, and Bcl-2 in MCF-7 and WEHI-164 cancer cells, qRT-PCR was carried out." (PMID 33122979, 2020). "It has been reported that survivin and XIAP are able to form an IAP-IAP complex to stabilize both of them and synergistically antagonize the activity of Caspase 9 in cancer cells." (PMID 32381104, 2020). "Epigallocatechin-3-gallate also considerably enhanced caspase-3 and caspase-9 activities and evidently increased the protein levels of Bax, cleaved caspase-9, cleaved caspase-3, in cancer cells." (PMID 32660101, 2020). "Several studies have reported that betulin shows selective inhibitory effects on proliferation of several cancer cells by inducing caspase-3- and caspase-9-mediated apoptosis." (PMID 31887988, 2019). "Its oxidant action can lead to ROS generation, caspase-3 and caspase-9 activation, apoptosis induction, and inhibition of the growth of cancer cells, which is essential in cancer prevention and the oncogenic process." (PMID 31428231, 2019). "Exposure to Raptinal showed cytotoxic effects in various cancer cell lines and triggered rapid processing of caspase-9." (PMID 31324752, 2019). "Based on this figure, activation of caspase 9 was higher than caspase 8 in both types of cancer cells." (PMID 30728391, 2019). "Our results suggest that strophanthidin treatment in cancer cells led to the overexpression of the initiator caspase 9 and further led to the activation of execution caspases including caspases 3 and 7, which eventually induced apoptosis." (PMID 32010609, 2019). "In the intrinsic apoptotic pathway, inhibited activation of caspase-9, as well as downstream executor caspases-3, can also usually lead to cancer treatment failures." (PMID 31871929, 2019). "CR again showed the weakest activation, increasing caspase 9 activation by approximately 1.2-fold in all three cancer cell lines." (PMID 31771155, 2019). "The pro-apoptotic effect was associated with the activation of caspase 3 and caspase 9 and cleavage of PARP, suggesting that Kaempferol treatment chemo-sensitized resistant cancer cells to apoptosis through caspases-dependent mechanisms." (PMID 30655588, 2019). "We identified miR-96-5p which possesses dual anti-apoptotic/pro-angiogenic functions by targeting caspase-9 in cancer cells and the anti-angiogenic tyrosine-phosphatase PTPN9, highly downregulated in the choroid." (PMID 31188886, 2019).
cancer (continued). "The results indicated that compound 1 was able to significantly decrease MMP and also increased caspase 9 activity in three human carcinoma cell lines." (PMID 31089373, 2019). "Active caspase-9 and active caspase-8 were also present in the treated cancer cells, though the numbers of cells positive to caspase-9 detection were significantly higher than those that were positive to caspase-8." (PMID 30304821, 2018). "In PEPE2-incubated T24 and J82 cells, the apoptosis-activator Bax level was increased while the anti-apoptotic Bcl-2 amount was decreased and thus, the pro-caspase-9 level dwindled, implying that the mitochondrial pathway was related to cancer cell apoptosis." (PMID 29702555, 2018). "It is known that highly invasive cancer cells are protected from apoptosis by increasing of various anti-apoptotic molecules including Caspase-9 protein." (PMID 30680070, 2018). "Accordingly, our molecular investigations unveil a consistent upregulation of cleaved PARP, caspase 3, and caspase 9, which has been observed in cancers treated with AZD1775 or cisplatin." (PMID 29977914, 2018). "TH treatment groups were found to have a lower anti-apoptotic proteins (E2, ESR1 and Bcl-xL) expression and a higher pro-apoptotic proteins (Apaf-1 and Caspase-9) expression at serum and on cancer tissue level (p < 0.05)." (PMID 28399853, 2017). "We demonstrated that TTM increased docetaxel cytotoxicity in MDR cancer cells by enhancing apoptosis as shown by high cleaved-caspase-9/3 and cleaved-PARP levels." (PMID 29254218, 2017). "Myrtucommulone (MC), a nonprenylated acylphloroglucinol present in the leaves of myrtle (Myrtus communis), is able to induce apoptosis in cancer cell lines via the mitochondrial cytochrome c/Apaf-1/caspase-9 pathway." (PMID 28914774, 2017). "Failing to activate caspase-9 has profound physiological and pathophysiological outcomes, leading to degenerative and developmental disorders even cancer." (PMID 28177918, 2017). "Monascus purpureus also decreased reactive oxygen species derived from mitochondria in cancer cells, and cellular apoptosis was induced via activation of caspase-9." (PMID 29203960, 2017). "We hope that our concerns will be helpful for further clinical studies addressing the roles of caspase-9 and its regulators demanded to identify more effective solutions to overcome intrinsic apoptosis-related diseases especially cancer." (PMID 28177918, 2017). "We found that Caspase-9 and Caspase-3 activity was noticeably up-regulated by juglanin treatment compared to the control group in cancer cells." (PMID 29212196, 2017). "In the present study, cancer-bearing rats showed reduced expression of caspse-3 and caspase-9 as compared to normal control rats." (PMID 27187346, 2016). "Recent studies have revealed C. spinosa induced apoptosis via mitochondrial cytochrome c release and caspase-9 and caspase-3 activation in cancer cell lines (Yu-Bin and Lei, 2014 ▶)." (PMID 27761417, 2016). "Our investigation indicated that compound 3c effectively inhibited cancer cells growth at the low concentration and subsequently led the cells to enter the apoptotic pathway which was indicated by cleavage of caspase 9, caspase 8, caspase 3 and PARP." (PMID 27625151, 2016). "The proapoptotic proteins Caspase-9 and PP2Acα are functionally related in a direct interaction, which constitutes a promising target for cancer therapy." (PMID 27152197, 2016). "Our results revealed that exposure to DEN and DEN-HPβCD complex has significantly increased the levels of caspase 9 and 3 compared with the untreated cancer cells." (PMID 27763535, 2016).